LPXN (leupaxin)
Description:
Transcriptional coactivator for androgen receptor (AR) and serum response factor (SRF). Contributes to the regulation of cell adhesion, spreading and cell migration and acts as a negative regulator in integrin-mediated cell adhesion events. Suppresses the integrin-induced tyrosine phosphorylation of paxillin (PXN). May play a critical role as an adapter protein in the formation of the adhesion zone in osteoclasts. Negatively regulates B-cell antigen receptor (BCR) signaling.
Synonyms: LDPL
Tractability: Antibody: its Gene Ontology location is reachable by antibodies, with high confidence; UniProt places it where antibodies can reach, with medium confidence. PROTAC: ubiquitination databases record sites on it; its protein half-life has been measured.
Gene: Protein-coding gene on chromosome 11 (58,526,871 to 58,578,220, reverse strand). Ensembl gene ENSG00000110031.
Subcellular location: Cytoplasm; Cell junction, focal adhesion; Nucleus; Cytoplasm, perinuclear region; Cell projection, podosome; Cell membrane
Subcellular location (Human Protein Atlas): Focal adhesion sites; Cytosol; Nuclear speckles
Gene Ontology:
Molecular function: protein binding; transcription coregulator activity
Biological process: negative regulation of B cell receptor signaling pathway; negative regulation of cell adhesion; cell adhesion; endothelial cell migration; protein-containing complex assembly; signal transduction; substrate adhesion-dependent cell spreading; regulation of cell adhesion mediated by integrin
Cellular component: cytoplasm; cytosol; focal adhesion; membrane; nuclear speck; nucleus; plasma membrane; podosome; cell-cell junction; perinuclear region of cytoplasm
Genetic constraint (gnomAD): Loss-of-function variants: 21 observed, 38.41 expected, observed/expected ratio (o/e) 0.55, 90% interval 0.39 to 0.79. The upper end of that interval is the gene's LOEUF score, 0.79, which puts it in group 3 of 6, group 1 being the genes least tolerant of losing a copy. Missense variants: 405 observed, 437.89 expected, observed/expected ratio (o/e) 0.92, 90% interval 0.85 to 1. Synonymous variants: 143 observed, 155.52 expected, observed/expected ratio (o/e) 0.92, 90% interval 0.8 to 1.06.
Homologues: Orthologues: chimpanzee LPXN (98% identical), macaque LPXN (98% identical), rabbit LPXN (89% identical), pig LPXN (86% identical), mouse Lpxn (85% identical), rat Lpxn (85% identical), guinea pig LPXN (82% identical), zebrafish lpxn (49% identical), Drosophila melanogaster Pax (48% identical), Caenorhabditis elegans pxl-1 (39% identical), Drosophila melanogaster CG34325 (18% identical), Drosophila melanogaster CG31988 (17% identical), and 4 more. Paralogues in human: PXN (58% identical), TGFB1I1 (47% identical).